JAK1 (Janus kinase 1)
Diseases named in the same sentence as JAK1 in open-access papers (continued):
Sharing a sentence is not in itself a finding about the gene and the disease.
tumor (continued). "Loss-of-function (LOF) mutations of JAK1, a member of the JAK kinase family, were frequently observed in EC, indicating that JAK1 may act as a tumor suppressor, at least in EC." (PMID 36376931, 2022). "Similarly to the change in the TLS status between samples, a JAK1 amplification appeared on the lung residual tumor." (PMID 35278076, 2022). "JAK1 and JAK2 mutations have also been implicated in affecting the tumour immune microenvironment." (PMID 35228677, 2022). "Osteoclast-secreted IL-19 activates JAK1/STAT3 signaling in IL20RB-expressing tumor cells." (PMID 36006737, 2022). "Results illustrated that STAT3 may be influenced during the tumorigenesis process of lung GGO as it is expressed higher in the tumor tissues than in normal lung tissues, while the trend of JAK1 seems to be consistent with that of IL-6." (PMID 34568032, 2021). "Several signaling pathways have been implicated in tumor-associated molecular alterations that contribute to the immune suppression of the TME, such as Kirsten rat sarcoma viral oncogene (KRAS), focal adhesion kinase (FAK), and Janus kinase-1/2 (JAK1/2)." (PMID 34897277, 2021). "It has been preliminary elucidated that IL-6 secreted by tumor cells could restrict the activity and function of NK cells through the JAK1 pathway." (PMID 34568032, 2021). "Tumor cells are associated with molecular alterations, including, but not limited to, mutations of Kirsten rat sarcoma viral oncogene (Kras), focal adhesion kinase (FAK), and Janus kinase 1/2 (JAK1/2), which directly influence the TIME and immune function." (PMID 33608497, 2021). "However, extrapolating from its function in other contexts, it is likely upregulating a T cell-mediated anti-tumor response through the JAK1/STAT1 pathway." (PMID 34122442, 2021). "The reason may be inactivation of Janus kinase 1 (JAK1), which leads to the decrease of PD-L1 expression, thereby tumor cells lack the sensitivity to PD-1 antibody treatment, resulting in inherent drug resistance." (PMID 33633793, 2021). "Abnormal JAK1 expression either promotes or suppresses tumour growth." (PMID 34587898, 2021). "PIVKA-II binds to the hepatocyte growth factor receptor, c-MET, leading to tumour growth, invasion and tumour metastases via the JAK-1/STAT3 and ERK 1/2 MAPK signalling pathways, whereas AFP is thought to be more a marker for hepatic progenitor cells or their subtypes." (PMID 34853657, 2021). "Additionally, Ibrutinib-resistant primary CLL cell growth was inhibited by Cerdulatinib, and these anti-tumor effects were proposed to be linked to inhibition of BCR, IL-4/Jak1/Jak3/Stat6 and IL-6/Jak1/Jak2/Stat3 signaling." (PMID 34680353, 2021). "Knowing that CD8+ T cells were the mediator of tumor control we next sought to determine whether CD8+ TILs exhibited improved effector functions in the context of IFNγR2- or Jak1-mutant tumors." (PMID 32001684, 2020). "Our study revealed the potential role of JAK1 in tumor immunology and its prognostic value in LUAD." (PMID 33323549, 2020). "Despite high tumor mutational burden (TMB) being often considered as a marker of responsive anti-PD1/PDL1 therapy, studies revealed that the resistance of PD1/PDL1 blockade in some high-mutated tumors was probably attributed to the JAK1/2 mutations." (PMID 32793604, 2020). "As the tumor grade increased, the expression of JAK1 decreased significantly." (PMID 33323549, 2020). "To test this hypothesis, we retrovirally restored expression of PD-L1 in IFNγR2- and Jak1-mutant tumor cells." (PMID 32001684, 2020). "In summary, our findings revealed that genistein, a tyrosine kinase inhibitor, inhibits EGFR expression, resulting in the restriction of the Akt and JAK1/2 signaling pathways, thereby suppressing cell proliferation and inducing tumor cell apoptosis in vitro and in vivo." (PMID 32276266, 2020). "However, the potential role of JAK1 in tumor immune infiltration and the prognosis of LUAD remains ambiguous." (PMID 33323549, 2020).
tumor (continued). "All 7 nonresponders harbored either JAK1 (6 tumors) or B2M mutations (1 tumor), while only 1 of the 3 responders harbored a JAK1 mutation (Fisher exact test, two-sided P = .067)." (PMID 32494760, 2020). "The abnormal expression of JAK1 was observed in multiple tumor tissues." (PMID 33323549, 2020). "AH057, the best JAK inhibitor identified, effectively blocked the JAK/STAT pathways by directly inhibiting JAK1/2 kinase activities, and led to compromised cell proliferation and invasion, increased apoptosis, arrested cell cycles, and impaired tumor progression in vitro and in vivo." (PMID 32895373, 2020). "The tumor cells with JAK1/JAK2 gene mutation were not sensitive to the killing effect of IFN, and the expression of PD‐L1 was downregulated, making the tumor cells resistant to PD‐1/PD‐L1 monoclonal antibody." (PMID 32875727, 2020). "Homozygous mutation of JAK1/2 was detected in post-treatment samples collected from melanoma patients who had tumor progression after initial response, suggesting clonal selection and proliferation of JAK-inactive tumor cells after applying the PD1 blockade." (PMID 32793604, 2020). "Unfortunately, mutations in (JAK1/JAK2) or class I MHC molecules (TAP2, B2M) and other still unknown signaling molecules can promote an inadequate immune response against tumours." (PMID 30670049, 2019). "Furthermore, the number of tumor promoting CD45+CD11b+CD206+ M2 macrophages was lowered upon JAK1/2 inhibition." (PMID 31407334, 2019). "This expression was dependent on activation of either NF-κB, JAK1/JAK2 or BTK pathways since these pathways were activated in tumor B-cells and ex vivo treatment with the inhibitory molecules PHA-408, ruxolitinib and ibrutinib led to decrease of its expression." (PMID 31382969, 2019). "JAK1 expression was analyzed via the Oncomine database and Tumor IMmune Estimation Resource site." (PMID 31790361, 2019). "Notably, the direct anti-tumor effects of BO-112 are abrogated in the B16 Jak1-KO compared to wildtype B16 tumors both in vitro and in-vivo." (PMID 30400822, 2018). "Importantly, the stable overexpression of Jak1, a key player in tumor cell response to anti-tumor immune attacks, reversed flavopiridol-induced resistance to IFN and FasL treatments." (PMID 30353012, 2018). "Furthermore, myricitrin has been shown to attenuate tumour promoting-induced activation of c-fos and activator protein-1, and to inhibit JAK1/STAT3 pathways." (PMID 29523111, 2018). "Thus, INCB053914 synergistically enhanced the inhibitory potency of the JAK1-selective inhibitor, itacitinib, and the JAK1/2-selective inhibitor, ruxolitinib, on tumor growth in xenograft models of MM." (PMID 29927999, 2018). "Lacking one allele of Jak1 impaired the ability of NK cells to control the tumor growth as illustrated by increased tumor size and tumor weight in Jak1fl/+Ncr1Cre." (PMID 30671064, 2018). "LOH for JAK1 was detected in 25% (15 of 59) and for JAK2 in 76% (45 of 59) of the cell lines suggesting a high risk of resistance development in the course of an effective anti-tumour T-cell response." (PMID 28561041, 2017). "Analyzing TCGA and CCLE expression data with GSEA, we confirmed indirectly the underlying biochemistry in human tumors samples by showing that expression of response genes for IFN and IL-6 families of cytokines are reduced in tumor samples and cell lines with JAK1 frameshifts." (PMID 29121062, 2017). "Tumor methylation data were used to build a methylation signature of PTEN loss in our cohort, which was confirmed in TCGA, and included CpGs in ATP11A, GDNF, JAK1, JAM3, and VAPA." (PMID 29137428, 2017). "And, in addition, and based on the results of the on-going phase I trial, that the addition of the JAK1/2 inhibitor ruxolitinib in a pulsatile fashion to [dasatinib + afatinib] may provide additional tumor control and patient benefit." (PMID 26934000, 2016).
tumor (continued). "It has been suggested that the interferon-γ-induced activation of JAK1 and JAK2 signaling pathway could suppress the tumor cell susceptibility to NK cells through up-regulation of PD-L1 expression." (PMID 27736796, 2016). "Moreover, inhibition of expression of JAK1 or STAT1 abrogated the ability of IFNγ to upregulate PD-L1 in the tumor cell, and reduced the ability of these cells to hamper NK-mediated immunotherapy." (PMID 27366948, 2016). "Additionally, phosphorylated STAT3 in cancer-associated fibroblasts (CAFs) drives angiogenesis and tumor growth, and phospho-STAT6 supports M2 macrophage polarization through JAK1 signaling, emphasizing the immunoregulatory impact of phosphorylation in the tumor microenvironment." (PMID 41359051, 2025). "For instance, scutellarin was found to disrupt tumor-associated angiogenesis by reducing transcription factor AP-1, while chrysin contained remarkable anti-angiogenesis properties through inhibiting VEGF/VEGFR2 expression and the phosphorylation of factors, e.g., JAK1 and STAT3 in HUVECs." (PMID 39860127, 2025). "Similarly, the efficacy of metabolic interventions in KEAP1-mutant tumours may be modulated by the gut microbiome, while microbiome-based interventions might help restore immune function in JAK1/2-mutant cases." (PMID 40277912, 2025). "Thus, Jak1 deletion directly averts PD-L1 protein expression, devoiding the tumor cell of a primary target of immune checkpoint blockade, and suppresses T cell infiltration in the tumor microenvironment (TME)." (PMID 38427670, 2024). "In contrast, PD-PDX kinases with potential to be restored by the addition of MSCs include ACVR1C (ALK7), MAP3K14 and ROR1, which may be inhibitors of tumour growth, and JAK1, involved in the STAT3 signalling pathway characteristic of the inflammatory molecular subclass of CCA." (PMID 39492622, 2024). "On the other hand, JAK1 could behave as an oncogene or tumor suppressor under certain conditions." (PMID 37895906, 2023). "Together, these data suggest that miR-494-5p physically inhibits the expression of JAK1 at the translational level as well as in migration and invasion, supporting the hypothesis of miR-494-5p as an early tumor suppressor and inhibitor of early steps of metastasis in CRC." (PMID 38201452, 2023). "Loss-of-function mutations in JAK1/2 may play an important role in the lack of response to PD-1 inhibitors due to the reduced ability of immune T cells to recognize tumor cells." (PMID 38023206, 2023). "Furthermore, in a panel of representative tumor cells (HCT‐116, A549, MAD‐MB231, AGS, SK‐Mel‐28, HeLa and Huh7), EHBP1L1 protein expression level was positively related to that of JAK1, suggesting that the EHBP1L1‐JAK1 axis is common among multiple tumor types." (PMID 36775874, 2023). "Furthermore, we found that the presence of the two JAK1 frameshift mutations was significantly associated with a lower IFN-γ expression compared to tumours without those JAK1 frameshift mutations (p = 0.036)." (PMID 36870947, 2023). "Some studies have reported that programmed death-ligand 1 (PDL1), tumor mutational burden (TMB), mismatch repair, and CD8+T cells may be potential biomarkers for efficacy prediction, whereas Janus kinase 1 (JAK1), JAK2, and beta-2-microglobulin truncation may be predictors of primary resistance." (PMID 38023206, 2023). "Although inconclusive, numbers of ICI-resistant markers have been proposed for MSI-H tumours, including low TMB, Janus kinase (JAK1/2/3) mutations, loss of beta-2-microglobulin (B2M) that could impair antigen presentation by class I major histocompatibility complex." (PMID 35842545, 2022). "Resistance mechanism to anti-PD-1 has been recently proposed to be associated with tumor-associated macrophages that could bypass the targeting of T cells or with mutation in key signaling pathways such as JAK1/2 kinases inducing IFNγ lack of response." (PMID 35339889, 2022).
tumor (continued). "Lastly, we examined the frequency of somatic copy number alterations (SCNA) associated with regulation of anti-tumor immune responses in pre-clinical and clinical studies: gains in MYC16, losses of PTEN17 and gains or losses in interferon pathway genes (PDCD1, STAT1, JAK1, and JAK2)." (PMID 34446728, 2021). "However, the potential role of JAK1 in tumor immune infiltration and the prognosis of LUAD remains unclear." (PMID 33323549, 2020). "In addition, of the 7 nonresponders, 4 harbored two mutations of JAK1 (3 tumors) or B2M (1 tumor), possibly reflecting biallelic inactivation of these genes." (PMID 32494760, 2020). "We next ascertained that the striking anti‐tumor effect of bazedoxifene treatment also extended to the epithelium of the small intestine, which is also susceptible to the therapeutic benefit conferred by inhibition of the IL11/STAT3 signaling axis at the level of the gp130‐associated JAK1/2 kinases." (PMID 30885958, 2019). "Thus, JAK1 mediated anti-proliferative signaling of IL-6; implying that the strong silencing of JAK1 expression in parental LNCaP cells possibly contributed to their thriving in an inflammatory, IL-6-rich tumor micro-environment." (PMID 29441069, 2018). "In addition, silencing of JAK1 in a variety of tumor cell types, or treatment of these cells with JAK inhibitors, induced increased secretion of IFNγ by co-cultured NK cells and enhanced susceptibility of the tumor cells to NK-mediated lysis." (PMID 27366948, 2016). "On the other hand, in this study clearance of adenovirus was delayed in ruxolitinib-treated normal animals, which makes it difficult to predict the overall impact of JAK1-inhibitors on tumor therapy where prolonged virus presence might translate to better therapeutic efficacy." (PMID 28548066, 2014). "Moreover, a recent study indicated that the glycoprotein 130 (gp130)-Janus kinase 1(JAK1)-signal transducer and activator of transcription 3 signalling pathway acts in CAFs and nearby tumour cells in a positive feedback fashion, thereby increasing their actomyosin contractility." (PMID 24216702, 2013). "SOCS3 overexpression or pharmacologic inhibition of JAK1/STAT3 markedly suppressed HIF-2α expression and tumor progression both in vitro and in vivo." (PMID 41874563, 2026). "Specifically, IL-6 induces an immunosuppressive state via the JAK1/STAT3 pathway, which inhibits cytotoxic T-cell differentiation and anti-tumor activity." (PMID 41019062, 2025). "Conversely, upon administration of ADRB2 blockers, the expression level of KLF4, p-JAK1, and p-STAT6 was reduced, along with a decrease in the proportion of pro-tumoral macrophages in the tumor microenvironment." (PMID 40276761, 2025). "Results showed that the expression levels of p-JAK1 and p-STAT6 in the tumor tissue of the sleep deprivation group were significantly upregulated, while ICI118,551 inhibited the expression of p-JAK1 and p-STAT6." (PMID 40276761, 2025). "To further evaluate the clinical value of p-ACAP4Y843 in HCC, we performed HE and immunohistochemical staining of HCC tumor tissues and adjacent tissues using antibodies against ACAP4, p-ACAP4Y843, JAK1, and p-JAK1." (PMID 39744421, 2025). "Mechanistically, METTL3 enhances the translation efficiency of Jak1 mRNA through m6A modification, thereby activating the JAK1-STAT3 signaling pathway and facilitating the formation of an immunosuppressive tumor microenvironment." (PMID 40567896, 2025). "The m6A‐YTHDF1 axis increases JAK1 protein translation efficiency and subsequent STAT3 phosphorylation, thus forming the METTL3/m6A/JAK1/STAT3 axis, which enhances TIMs’ immune suppressive functions and facilitates tumor immune evasion." (PMID 40443721, 2025). "Ruxolitinib, a selective JAK1/2 kinase inhibitor known to suppress JAK-STAT signaling, was used to assess the role of tumor-intrinsic IFN signaling in the elevated release of ICAM-1 and CXCL10." (PMID 40861475, 2025).
tumor (continued). "For example, after AEA activates CB2 receptors, it promotes tumor progression by inhibiting the JAK1/STAT1/3 signal of tumor-killing T cells and suppressing anti-tumor immunity." (PMID 41154659, 2025). "Taken together, these outcomes indicate that PD-L1 blockade treatment normalizes tumor vasculature and inhibits neovascularization by decreasing the expression of Tie2 and ANGPT2 through a JAK1/2-dependent mechanism." (PMID 40370455, 2025). "In tumor-infiltrating myeloid cells (TIMs), METTL3-mediated m6A modification of Jak1 mRNA enhances JAK1 protein translation efficiency through the m6A-YTHDF1 axis, leading to increased phosphorylation of STAT3." (PMID 40244180, 2025). "We observed significant up-regulation of IL-15 signaling genes in tumor-infiltrating NK clusters, including IL15, IL2RB, IL2RG, STAT5B, and JAK1." (PMID 40315330, 2025). "The results showed that the expression of KLF4, p-JAK1, and p-STAT6 was increased in the tumor tissue of the sleep deprivation group compared to the normal sleep group." (PMID 40276761, 2025). "In terms of tumor immunity, TPL reduced PD-L1 expression through the EGFR and JAK1/2-STAT1/3 signaling pathways in NSCLC cells." (PMID 40841966, 2025). "As BBR concentration increased, the anti-proteolytic ability of JAK1 protein gradually improved, suggesting that JAK1 protein is a potential direct molecular target for BBR’s anti-tumor activity." (PMID 41585886, 2025). "SNORA28 facilitates radioresistance by recruiting BRD4 to increase H3K9 acetylation at the LIFR promoter, which activates the JAK1/STAT3 pathway and promotes tumor cell proliferation." (PMID 41359051, 2025). "Several in vivo pre-clinical models and CRISPR screens support this observation, as cell lines with mutations in IFNγR or downstream signalling molecules such as JAK1/2 and STAT1 have been shown to sensitise the tumour towards improved ICB response." (PMID 39746898, 2025). "Circulating tumor DNA (ctDNA) and exosomal RNA can provide dynamic, non-invasive insights into tumor evolution and immune evasion pathways, such as acquired mutations in β2-microglobulin or JAK1/2, which are associated with resistance to immune checkpoint inhibitors." (PMID 40561796, 2025). "For instance, epigenetic silencing of interferon-stimulated genes in JAK1/2-mutant tumours has been shown to exacerbate ICI resistance and accelerate tumour progression." (PMID 40277912, 2025). "Our research revealed that MSGA activated JAK1/3-STAT1 and downregulated STAT3 phosphorylation to reprogram macrophages into an anti-tumor M1 phenotype." (PMID 40786029, 2025). "Subsequent experiments demonstrated that BBR targets JAK1 protein, inhibiting the IL-4-JAK1-STAT6 axis to suppress M2 polarization of tumor-infiltrating macrophages, thereby enhancing tumor suppression." (PMID 41585886, 2025). "Lactate accumulated in the tumor microenvironment upregulates the expression of METTL3 in TIM by lactating H3K18, thus methylating Jak1 mRNA, enhancing the translation efficiency of Jak1 protein and increasing its phosphorylation level." (PMID 40919129, 2025). "METTL3 further mediates m6A modification of JAK1 mRNA, and the m6A-YTHDF1 axis ultimately promotes JAK1 protein translation and STAT3 phosphorylation, facilitating CRC immune evasion and tumor progression." (PMID 39897556, 2025). "For example, secretion of VEGFA promotes angiogenesis and tumor growth, IL6 activates the STAT/JAK1 pathway enhancing cancer cell plasticity, and TGF‐β induces EMT, cell invasion capacity and resistance to treatment." (PMID 40411295, 2025). "We observed significantly reduced levels of JAK1 and MHC-I in tumors with high tumor-specific UBA1 expression compared with UBA1-low tumors." (PMID 39540840, 2025).